OR5I1 (olfactory receptor family 5 subfamily I member 1)
Description:
Odorant receptor.
Synonyms: OLF1; HSOlf1
Tractability: Antibody: UniProt places it where antibodies can reach, with medium confidence; UniProt predicts a signal peptide or a membrane-spanning region; its Gene Ontology location is reachable by antibodies, with medium confidence.
Gene: Protein-coding gene on chromosome 11 (55,935,456 to 55,936,400, reverse strand). Ensembl gene ENSG00000167825.
Subcellular location: Cell membrane
Pathways (Reactome):
Sensory Perception: Expression and translocation of olfactory receptors
Gene Ontology:
Molecular function: olfactory receptor activity; G protein-coupled receptor activity
Biological process: G protein-coupled receptor signaling pathway; sensory perception of smell; signal transduction; detection of chemical stimulus involved in sensory perception of smell
Cellular component: plasma membrane; membrane
Genetic constraint (gnomAD): Loss-of-function variants: 1 observed, 0.26 expected, observed/expected ratio (o/e) 3.81. That is too few expected variants to judge how well the gene tolerates losing a copy. Missense variants: 409 observed, 371.11 expected, observed/expected ratio (o/e) 1.1, 90% interval 1.02 to 1.2. Synonymous variants: 157 observed, 146.33 expected, observed/expected ratio (o/e) 1.07, 90% interval 0.94 to 1.23.
Homologues: Orthologues: chimpanzee OR5I1 (97% identical), macaque OR5I1 (95% identical), dog OR5I1B (90% identical), mouse Or5i1 (90% identical), rabbit OR5I1 (90% identical), rat Or5i1 (89% identical), dog OR5I1 (88% identical). Paralogues in human: OR5D18 (55% identical), OR5AP2 (55% identical), OR5AS1 (55% identical), OR5L2 (53% identical), OR5W2 (53% identical), OR5L1 (53% identical), OR5A1 (52% identical), OR5J2 (52% identical), OR9G4 (52% identical), OR9I1 (52% identical), OR5AR1 (52% identical), OR8J1 (51% identical), and 84 more.
Diseases named in the same sentence as OR5I1 in open-access papers:
OR5I1 is named in the same sentence as 1 disease in open-access papers, as found by Europe PMC text mining. Sharing a sentence is not in itself a finding about the gene and the disease. The quoted sentences say what the papers report.
cancer (1 paper, 2021). A tumor composed of atypical neoplastic, often pleomorphic cells that invade other tissues. "Confinement of all ORs, except for OR5I1, to the neutral “gray area”, indicates that there is no broad oncogenic reliance on multiple OR-mediated GPCRs, but that the ectopic expression of a specific OR may suffice to promote cancer cell growth." (PMID 33767353, 2021).